IL4 (interleukin 4)
Diseases named in the same sentence as IL4 in open-access papers (continued):
Sharing a sentence is not in itself a finding about the gene and the disease.
Stroke (98 papers, 2011 to 2026). Sudden impairment of blood flow to a part of the brain due to occlusion or rupture of an artery to the brain. "On the other hand, PPARγ agonists, which increase IL-4 in hippocampus, appear to reduce the risk of stroke." (PMID 35431903, 2022). "Histologic studies of white matter after stroke injury in IL-4-deficient mice revealed defective remyelination, which was restored by intranasal delivery of IL-4." (PMID 35887140, 2022). "Histological staining of the neuronal marker NeuN further demonstrated comparable tissue loss 35 d after stroke in IL-4- and vehicle-treated mice." (PMID 31226122, 2019). "Although these clinical and experimental data are correlative, the present series of in vivo and in vitro studies firmly establish a causal link between IL-4 repletion and white matter integrity in preclinical stroke models." (PMID 31226122, 2019). "In particular, the intranasal route enables CNS IL-4 delivery, which is expected to significantly reduce the risk of peripheral side effects and expedite the eventual translation of IL-4 treatment for stroke victims." (PMID 31226122, 2019). "A number of preclinical and clinical studies have reported an association between IL-4 levels and stroke pathology." (PMID 31226122, 2019). "Deficiency of endogenous IL-4 exacerbated white matter disruption, whereas intranasal IL-4 treatment—even when delayed until 6 h post-stroke—improved the structural and functional integrity of white matter." (PMID 31226122, 2019). "IL-4 deficiency in knockout mice resulted in greater deterioration of white matter over 14 d after stroke." (PMID 31226122, 2019). "Simultaneously, Genetics as a risk factor for stroke have also been confirmed, and some genetic polymorphisms such as MTHFR, ApoE, P-selectin and interleukin-4 gene have been shown to be associated with the risk of stroke." (PMID 29383136, 2017). "In addition, IL-4 deficiency is associated with aggravation of brain injury and neurological defects in a stroke animal model indicating its protective role in ischemic stroke." (PMID 35887140, 2022). "Studies of animal models have further indicated that IL-4 might also play a role in atherosclerosis via the induction of inflammatory responses, while atherosclerosis itself is a leading pathogenic mechanism of stroke." (PMID 31546833, 2019). "Lower concentrations of IL-4, IL-6, and TNF-α were negatively correlated with stroke patients suffering from hyperhomocysteinemia (IL-4: P = 0.015, χ2 = 6.040; IL-6: P = 0.015, χ2 = 6.038; TNF-α: P = 0.016, χ2 = 6.243)." (PMID 38287458, 2024). "Serum IL-1β and IFN-γ were elevated in all four phases following stroke onset while IL-4 was elevated exclusively in the recovery phase (48-96 h) (p<0.05)." (PMID 38870172, 2024). "Only for IL-4 (p < 0.001, η2 = 0.151, large effect size) were higher levels found in people with sCeAD compared to other stroke aetiology groups." (PMID 38802464, 2024). "IL-4 is a STAT6 activator that shifts microglia/macrophages toward an anti-inflammatory phenotype following stroke and has been reported to promote neurogenesis, tissue protection, and repair." (PMID 37759938, 2023). "The strong anti-inflammatory properties of IL-4 play an important role in determining the prognosis of stroke." (PMID 36793730, 2023). "This IL4 enhanced expression by female microglia can be behind the differential neuroprotective function of IL4 reported for female mice subjected to experimental stroke." (PMID 36779011, 2023). "Among them, IL-4 increases significantly during the acute phase of stroke, promoting the polarization of M2 microglia, inhibiting pro-inflammatory cytokines, and affecting neuronal excitability." (PMID 38089678, 2023). "IL‐13 and IL‐4 have been shown to increase IL‐6 production, and elevations in both IL‐13 and IL‐4 demonstrate reparative effects following stroke in mice models." (PMID 36478506, 2023).
Stroke (continued). "IL-4 is widely thought to be crucial during the acute stage of stroke, with dramatically increased serum levels hours after stroke onset." (PMID 36793730, 2023). "We are skeptical that IL-4 is actually involved in the development of brain Tregs because IL-4 expression was barely detectable in the brain in vivo in our stroke experiments." (PMID 35911740, 2022). "In contact co-cultures involving monocytes isolated from stroke blood, there was a statistically significant increased release of IL-4 as compared to co-cultures involving healthy control monocytes (p < 0.05)." (PMID 36277912, 2022). "Our recent animal stroke model showed that interleukin (IL)-4 and IL-13 released by microglia are converted into monocyte-derived macrophages." (PMID 35634277, 2022). "A study indicated that Interleukin-4 improves long-term neurological outcomes after stroke by reducing inflammation in the core and activated astrocytes in the penumbra." (PMID 35350431, 2022). "Another study found that immunomodulation with IL-4 is a promising approach to promote long-term functional recovery after stroke through M2 phenotype induction in microglia/macrophages." (PMID 35350431, 2022). "In trans-well co-cultures of MSCs and monocytes isolated from stroke patients, we found statistically significant increased levels of IL-4 and MCP-1, and decreased levels of IL-6, IL-1β, and TNF-α." (PMID 36277912, 2022). "Serum IL-4 levels are also known to increase significantly in patients several hours after a stroke." (PMID 36012189, 2022). "For anti-inflammatory cytokines, a relatively homogenous pattern was seen; IRF5 CKO induced a significant increase in both IL-4 and IL-10 levels, and IRF4 CKO caused significant reduction in IL-4 and a decrease trend in IL-10 level, in stroke groups." (PMID 35963621, 2022). "T cells lacking Bim have a reduced production of several pro- (e.g. IL-6, IFN-γ) and anti- (e.g. IL-4, IL-10) inflammatory cytokines, which have been shown to play critical roles in stroke injury." (PMID 35149957, 2022). "Our finding indicated that baseline serum CRP, GDNF, IFN-γ, IGFBP-6, IL-4, LYVE-1, MMP-2, PAI-1, and PDGF-AA levels were associated with post-thrombolytic sICH in stroke." (PMID 35173671, 2022). "Recent animal and clinical researches have demonstrated the importance of IL-4 in the acute phase of stroke." (PMID 35173738, 2022). "Studies on stroke and multiple sclerosis have shown that IL-4 has a protective factor against spinal cord injury." (PMID 35153973, 2021). "Interleukin (IL)-1beta, TNF-alpha, and IL-4 mRNA levels were higher, while IL-10 mRNA levels were reduced in total monocytes from patients versus controls, at either 24 h or 48 h after stroke." (PMID 34201498, 2021). "Evidence shows that the blockade of IL-4 abrogates the promoting role of hyperforin in post-stroke angiogenesis, neuronal regeneration, and functional rehabilitation." (PMID 33967696, 2021). "In animal models of ischemic stroke, exogenous IL-4 administration after tMCAO ameliorated post-stroke motor and behavioral functions, while its effect on stroke size was not always clearly detectable." (PMID 33770265, 2021). "Previous studies showed that IL-4 serves as an early endogenous neuroprotective mechanism soon after stroke onset and is important in the acute stages of stroke." (PMID 32431711, 2020). "In vivo, IL-4 promotes M2-like macrophage phenotypes after stroke, spinal cord injury (SCI), and peripheral nerve injury (PNI) at doses ranging from 250 to 500 ng." (PMID 32563258, 2020). "Whereas IL-10 producing lymphocytes were upregulated at admission, the proportion of T lymphocytes producing IL-4 increased all over the 90 days from the onset of stroke." (PMID 32719588, 2020). "A significant improvement in white matter microstructure was only observed in IL-4-treated animals in later stages of recovery (28 and 35 d after stroke)." (PMID 31226122, 2019).
Stroke (continued). "Vehicle or IL-4 treatment in PPARγ-OPC KO mice resulted in similar neuronal tissue loss and white matter lesion 35 d after stroke." (PMID 31226122, 2019). "Further characterization of the optimal regimen of IL-4 treatment for stroke would accelerate its clinical translation." (PMID 31226122, 2019). "IL-4 treatment increased the numbers of BrdU+APC+ cells or total BrdU+ cells after stroke in mice fed with the control diet." (PMID 31226122, 2019). "In contrast to our findings in the newborn, previous studies in adult stroke models have shown that IL-4 is helpful for functional recovery." (PMID 31839002, 2019). "In our study, we found that serum concentrations of IL-4, IL-5 and IL-9 were significantly elevated in minor stroke patients and negatively related to the NIHSS score." (PMID 31164999, 2019). "IL-4-treated and vehicle-treated stroke mice showed comparable reductions in latencies to contact and remove adhesive tape from the paw at 3 d after stroke, suggesting similar initial deficits in dexterity across groups." (PMID 31226122, 2019). "First, longitudinal DTI revealed similar reductions in FA values shortly after stroke in vehicle or IL-4-treated mice, indicating comparable degrees of initial white matter injury during the early/acute phase." (PMID 31226122, 2019). "Next, we measured the potential correlation between white mater integrity and behavioral performance after stroke in vehicle or IL-4-treated mice." (PMID 31226122, 2019). "For example, subcutaneous IL-4 application at 2 μg/kg/d or intracerebroventricular application of IL-4 at 60 ng/d significantly improved long-term outcomes after stroke." (PMID 31226122, 2019). "IL-4 is mostly known as an anti-inflammatory cytokine and IL-5 have been shown to suppress post-stroke inflammation." (PMID 31164999, 2019). "In IL-4-treated stroke mice, we observed an anti-inflammatory phenotypic change in microglia/macrophages, which is known to promote remyelination after CNS injury." (PMID 31226122, 2019). "Th2 type cytokines including interleukin-4 (IL-4) and interleukin-5 (IL-5) were found to play beneficial roles in the repair of brain damage, suppress post-stroke inflammation, and have the capability to induce neurotrophic factors in astrocytes." (PMID 31164999, 2019). "Intranasal delivery of IL-4 nanoparticles after stroke robustly promoted oligodendrogenesis, enhanced white matter integrity, and improved long-term functional recovery." (PMID 31226122, 2019). "We also reported that IL-4 deficiency significantly impairs long-term sensorimotor and cognitive performance after ischemic injury, whereas IL-4 supplementation improves functional outcomes in two models of stroke." (PMID 31226122, 2019). "IL-4 is a key Th2 cytokine and has been extensively studied in adult models of stroke and multiple sclerosis where it is thought to be neuroprotective and anti-inflammatory." (PMID 31839002, 2019). "In contrast, the levels of anti‐inflammatory cytokines (IL‐4 and IL‐10) increased and peaked at 10 days of stroke." (PMID 29131464, 2018). "In our study, the serum levels of TNF-α, CRP, IL-4, and IL-10 were all significantly increased in stroke patients, whereas, the serum level of IFN-γ was decreased compared with that in control subjects." (PMID 27682880, 2017). "For example, M2-like microglia/macrophages were found to protect neurons from ischemic death in vitro, and IL-4 promoted long-term recovery after stroke in mice, possibly by inducing an M2-like macrophage phenotype." (PMID 28754163, 2017). "Delayed (6–7 days) elevation of IL-10, IL-4, and IL-17 in the post-acute phase of stroke was previously reported by other authors." (PMID 27829437, 2016). "Brain cytokine analysis at 24 h indicated that stroke resulted in substantially higher mean levels of IL-4, IL-6, TNF-α, IFN-γ, IL-10, and IL-17A in both C57Bl/6 and FVB mice." (PMID 25477780, 2014).
Stroke (continued). "A recent study of stroke in IL-4 knockout mice showed that IL-4 reduces the TH1 : TH2 cell ratio and infarct volume, and improves neurological outcome." (PMID 23691272, 2013). "The role of IL-4 in neuroprotection has been demonstrated in mouse models of Alzheimer's disease and stroke." (PMID 23404620, 2013). "The differentiation of helper lymphocytes into Th2 is promoted by interleukins IL-4 and IL-9, and their reduced expression may indicate an impaired humoral response in stroke patients." (PMID 40520895, 2025). "Furthermore, binary logistic model fitted for FO indicated Th1:Th2 cytokine ratio (IFN-γ:IL-4), vitamin D status, history of stroke, and ischemic heart disease as significant predictors of AIS prognosis." (PMID 38870172, 2024). "Furthermore, we observed noteworthy disparities in the plasma levels of IL-2, IL-4, IL-6, IL-10, TNF-α, and INF-γ between patients devoid of risk factors and those presenting with comorbid risk factors associated with stroke." (PMID 38287458, 2024). "Systemic administration of IL-4 could reduce ischemic lesion and improve neurological function after stroke." (PMID 36782269, 2023). "IL-4 is reportedly crucial for the neuroprotection of young female mice following stroke." (PMID 36793730, 2023). "IL-4 induces microglia M2 polarization and improves long-term neurological function after stroke." (PMID 37361996, 2023). "Stroke prognosis is significantly affected by IL-4’s potent anti-inflammatory effect." (PMID 36793730, 2023). "Several hours after the onset of stroke, the level of IL-4 in serum was observably increased." (PMID 35173738, 2022). "Earlier reports on the beneficial role of exogenous IL-4 application within the CNS as well as the upregulation of brain-endogenous IL-4 after stroke led to the notion that this immune cytokine may serve neuroprotective or repair-related activities." (PMID 35587822, 2022). "Additionally, PPARγ is essential for IL-4-induced oligodendrocyte progenitor cell differentiation and long-term functional improvements after stroke." (PMID 35173738, 2022). "This suggests that although IL-4 and IL-13 share the same receptor, they may function through completely different cells after a stroke." (PMID 35578342, 2022). "SNHG15, which is an IL-4-induced lncRNA in macrophages, uniquely represses K63-linked ubiquitination of TRAF2 to promote M2 macrophage polarization and thereby attenuates inflammatory responses after stroke." (PMID 34980176, 2022). "As IL-4 deficiency was shown to exacerbate brain damage and worsen neurological outcome 24 h after transient middle cerebral artery occlusion in animal stroke models, IL-4 is thought to function as an endogenous neuroprotective molecule immediately after stroke onset." (PMID 36012189, 2022). "CDC42 was negatively correlated with the National Institutes of Health Stroke Scale (NIHSS) score (p < 0.001), whereas, in patients with AIS (all p < 0.050), it was positively associated with Th2 cells and IL-4 but negatively correlated with Th17 cells and IL-17A." (PMID 35547377, 2022). "In a different study employing an animal models of stroke, hyperforin, the main active ingredient derived from H. perforatum, showed the ability to promote neuroangiogenesis and functional recovery by stimulating the production of IL-4, IL-6, and TGF-β1." (PMID 34356309, 2021). "However, EV membrane-bound IL4 levels were significantly correlated with stroke compared to healthy subjects (p = 0.038)." (PMID 34360613, 2021). "Therefore, elucidation of the IL-4 and related signaling pathways involved in the protective effect induced by treadmill exercise in a stroke model is needed." (PMID 34692788, 2021). "As mentioned, IL-4 alone has been delivered after stroke, SCI, and PNI." (PMID 32563258, 2020). "Additionally, in a stroke model, early intracerebral injection of IL-4 was able to inhibit M1 activation while enhancing M2 microglial activation and promoting neuro-functional recovery." (PMID 33013320, 2020).
Stroke (continued). "Importantly, IL-4 treatment still resulted in a significant enhancement of BrdU+APC+ oligodendrocyte regeneration in microglia/macrophage-depleted stroke mice." (PMID 31226122, 2019). "However, at later time points starting from 7–10 d after stroke, IL-4 treatment reduced the time spent touching and removing tapes in stroke mice, culminating in improved performance in the adhesive removal test." (PMID 31226122, 2019). "IL-4 deficiency exacerbates brain injury and neurological deficits in acute timeframes after transient middle cerebral artery occlusion (MCAO), implicating IL-4 as an endogenous protective mechanism in the early stages after stroke." (PMID 31226122, 2019). "As the IL-4 treatment was initiated 6 h after stroke, it remains possible that IL-4 may provide some degree of early protection." (PMID 31226122, 2019). "Cerebral IL-4 levels then return to baseline within 1 wk after stroke." (PMID 31226122, 2019). "IL-4 may be released from injured neurons and peripheral immune cells that have infiltrated the brain after stroke." (PMID 31226122, 2019). "Although IL-4 deficiency increased the loss of NeuN+ brain tissue at acute phases of stroke, it did not influence neuronal tissue loss at late stages." (PMID 31226122, 2019). "In the current study, we discovered that IL-4 is essential for white matter repair after stroke." (PMID 31226122, 2019). "IL-4-deficient mice displayed exacerbation of the loss in MBP and a further increase in the SMI32/MBP ratio compared to WT mice, suggesting that IL-4 is important in maintaining axonal myelination or promoting axonal remyelination after stroke." (PMID 31226122, 2019). "Finally, OPC-specific PPARγ KO (PPARγ-OPC KO) mice were used to confirm the importance of PPARγ signaling in IL-4-enhanced oligodendrogenesis in an in vivo stroke model." (PMID 31226122, 2019). "This was evidenced by a significant increase in the levels of multiple inflammatory cytokines including IP-10, KC, MCP-1, MIP-1α, MIP-1β, MIP-2, RANTES, IL-9, IL-4, and IL-12 (p70) within the infarct at eight weeks post stroke when compared to naïve brain tissue." (PMID 30417081, 2018). "Interestingly, we did not observe an effect of BML‐111 treatment on anti‐inflammatory cytokines IL‐10 and IL‐4 at 1 week post‐stroke, despite increased CD163+ microglia/macrophages." (PMID 28523230, 2017). "Further, IL-4 appears to have long-term neuroprotective effects after experimental stroke." (PMID 28936196, 2017). "Previous reports have shown that TNF-α, IFN-γ, IL-6, IL-17, IL-23, and some monocytes are detrimental in the pathologic process of stroke, whereas Treg cells, IL-4, IL-10, and TGF-β are major cerebroprotective modulators of post-ischemic inflammatory brain damage." (PMID 27682880, 2017). "The serum levels of TNF-α, CRP, TGF-β, IL-4, IL-6, IL-10, IL-17, and IL-23 were all increased on days 1, 3, and 7 after stroke when compared with levels in the control group (all p < 0.05); however, the content of IFN-γ was lower in stroke patients than in controls at each time point (p < 0.01)." (PMID 27682880, 2017). "IL-4 levels in brain are generally very low, but increase several hours after stroke onset." (PMID 28936196, 2017). "Il-4 (mostly regarded as anti-inflammatory cytokine) and IL-5 were found to play a beneficial role in brain repair, modulate microglial response, and suppress post-stroke inflammation." (PMID 27829437, 2016). "Stroke also results in a shift from pro-inflammatory Th1 to anti-inflammatory Th2 response in animal stroke models and a significantly lower ratio of IFNγ/IL-4-producing T cells in human patients." (PMID 23555048, 2013). "In addition, SNHG15 is an IL-4-induced macrophage LncRNA that uniquely inhibits K63 linked TRAF2 ubiquitination, thereby promoting M2 macrophage polarization and alleviating inflammatory response after stroke." (PMID 37153000, 2023).